ZNF587 (zinc finger protein 587)
Description:
May be involved in transcriptional regulation.
Synonyms: ZF6; FLJ14710; UBF-fl; FLJ20813
Tractability: PROTAC: ubiquitination databases record sites on it.
Gene: Protein-coding gene on chromosome 19 (57,849,841 to 57,865,117, forward strand). Ensembl gene ENSG00000198466.
Subcellular location: Nucleus
Subcellular location (Human Protein Atlas): Nucleoplasm; Nucleoli
Pathways (Reactome):
Gene expression (Transcription): Generic Transcription Pathway
Gene Ontology:
Molecular function: protein binding; DNA-binding transcription factor activity, RNA polymerase II-specific; RNA polymerase II cis-regulatory region sequence-specific DNA binding
Biological process: regulation of transcription by RNA polymerase II; regulation of DNA-templated transcription
Cellular component: nucleus
Genetic constraint (gnomAD): Loss-of-function variants: 8 observed, 8.41 expected, observed/expected ratio (o/e) 0.95, 90% interval 0.56 to 1.66. That is too few expected variants to judge how well the gene tolerates losing a copy. Missense variants: 468 observed, 634.27 expected, observed/expected ratio (o/e) 0.74, 90% interval 0.68 to 0.8. Synonymous variants: 145 observed, 210.15 expected, observed/expected ratio (o/e) 0.69, 90% interval 0.6 to 0.79.
Homologues: Paralogues in human: ZNF417 (98% identical), ZNF776 (52% identical), ZNF17 (43% identical), ZNF416 (42% identical), ZNF530 (42% identical), ZNF287 (35% identical), ZNF34 (34% identical), ZNF527 (33% identical), ZNF285 (32% identical), ZKSCAN7 (32% identical), ZNF214 (31% identical), ZNF852 (31% identical), and 38 more.
Diseases named in the same sentence as ZNF587 in open-access papers:
ZNF587 is named in the same sentence as 3 diseases in open-access papers, as found by Europe PMC text mining. Sharing a sentence is not in itself a finding about the gene and the disease. The quoted sentences say what the papers report.
lymphoma (1 paper, 2025). A malignant (clonal) proliferation of B- lymphocytes or T- lymphocytes which involves the lymph nodes, bone marrow and/or extranodal sites. "Along these lines, we have recently shown that depleting ZNF417 and ZNF587, two primate-specific KZFPs frequently upregulated in lymphoma cells, induces H3K9me3 loss and replication stress at their target sites." (PMID 40555235, 2025).
major depressive disorder (1 paper, 2024). An episode of depression lasting two or more weeks without an intervening episode of mania. "Interestingly, gene expression analysis on peripheral blood specimens from major depressive disorder (MDD) patients and healthy controls revealed an upregulation of ZNF587 in individuals with MDD, in line with publicly available microarray data." (PMID 38605603, 2024).
tumor (2 papers, 2010 to 2021). "Among which, only ZNF587 had the significant difference in expression profile in tumor tissues and normal tissues." (PMID 34670480, 2021).